TFEB (transcription factor EB)
Diseases named in the same sentence as TFEB in open-access papers (continued):
Sharing a sentence is not in itself a finding about the gene and the disease.
melanoma (continued). "Finally, we observed that the invasive potential of GNPTAB KO-WM1716 melanoma cell line can be stimulated by inhibition of TFEB using specific siRNA, recapitulating our observations made solely with transient gene interference." (PMID 38750105, 2024). "However, the mechanism in melanoma and pancreatic cancer is likely different because in pancreatic cancer cells, direct control of TFEB on Gls transcription has been observed." (PMID 37160873, 2023). "In the present study, we demonstrate a key role for TFEB in melanoma that is independent of BRAF mutation, which is a genetic trait that characterises ~52% of human melanomas." (PMID 37160873, 2023). "Dysfunction of TFEB has been observed in the pathogenesis of several diseases, including neurodegenerative disease, aging, kidney diseases, pancreatitis, Salmonella typhimurium infection, and melanoma." (PMID 35625599, 2022). "In addition, the canonical melanoma mutation BRAFV600E inhibits autophagy by phosphorylating and inactivating transcription factor EB (TFEB), the master transcriptional factor of autophagy, via downstream ERK." (PMID 36003368, 2022). "Publicly available ChIP-seq data for MITF in 501Mel and Colo829 human melanoma cells were analyzed in order to determine if MITF might be involved in directly regulating its own expression or that of TFEB and TFE3." (PMID 32881934, 2020). "Here we investigated the cross-regulatory relationship of MITF and TFEB in melanoma cells." (PMID 32881934, 2020). "Notably, the favorable response of TFEBS142A cells to PLX4720 was abolished when cells were treated with BafA1 or depleted of Beclin1, suggesting that TFEB-induced autophagy–lysosomal activation is required to elicit a response to BRAFi in melanoma." (PMID 30979895, 2019). "Thus, S142 phosphorylation by ERK plays a dominant role over S211 phosphorylation in TFEB regulation in BRAF-mutant melanoma." (PMID 30979895, 2019). "Although the role for TFEB in melanoma is still understudied, it would be interesting to investigate if blockage of this MAPK–TFEB pathway in combination with leucine starvation is a way to keep autophagy at bay and elicit caspase-dependent apoptotic cell death of melanoma cells." (PMID 27896217, 2016). "Therefore we cannot exclude that in melanoma a different isoform of TFEB could be expressed and differently regulated." (PMID 38750105, 2024). "Interestingly, the observation that a genetically induced reduction in TFEB level increased the antiproliferative effect exerted by a BRAF inhibitor suggests new possible therapeutic interventions targeting TFEB for managing melanoma and overcoming acquired resistance to standard therapies." (PMID 37160873, 2023). "In order to determine whether MITF and TFEB are able to influence each other’s expression, we investigated the effects of transiently overexpressing the two individual factors on their expression in 501Mel and Skmel28 human melanoma cell lines." (PMID 32881934, 2020). "Interestingly, another transcription factor that is related to TFEB, microphthalmia-associated transcription factor (MITF) has been shown to bind to the promoters of genes encoding lysosomal and autophagosomal proteins in melanoma." (PMID 32340261, 2020). "In our experiments, the PIKfyve inhibitor YM201636 and pyridinyl imidazole inhibitors SB202190 and SB590885 all promoted nuclear localization of TFEB, indicating that the drug-induced disruption of mTOR lysosomal tethering could inhibit mTORC1 activity in melanoma cells." (PMID 32531927, 2020). "In TFEB-deficient melanoma cells, BRAFi could no longer trigger autophagy activation, even though the ER stress machinery remained intact." (PMID 30979895, 2019). "We next determined whether TFEB plays an equivalent role in BRAFV600E melanoma resistant to BRAFi." (PMID 30979895, 2019).
melanoma (continued). "We therefore used 501mel human melanoma cells, in which we previously mapped genome-wide binding of MITF,64,72 to express Dox-inducible hemagglutinin (HA)-tagged TFEB and performed ChIP-seq using the highly specific HA antibody." (PMID 41275493, 2025). "This coordination links mTORC1 signaling with the endosomal–lysosomal system, making MITF a key regulator of melanoma plasticity and progression via control of TFE3, TFEB, and endosomal–lysosomal pathways." (PMID 41155412, 2025). "In prior studies, Dusp1 has been shown to impact mTOR in ovarian cancer, and TFEB, in turn, has been shown to negatively bind and regulate the DUSP1 promotor in melanoma." (PMID 39718832, 2024). "Further analyses revealed mTORC1-independent TFEB phosphorylation and inactivation by constitutively activated ERK in BRAFV600E melanomas, which can be reversed by BRAFi [41••]." (PMID 36670319, 2023). "TFEB is a repressor of dual-specific phosphatase-1 (DUSP-1), which is a key negative regulator of MAPK in mammalian cells, including melanoma cells." (PMID 37160873, 2023). "In melanoma cells, MITF and TFEB participate in cross-regulatory circuits, in which MITF enhances the expression of TFEB, while TFEB inhibits MITF expression." (PMID 37160873, 2023). "The knowledge that EGR1 expression is regulated by the MAPK signaling pathway prompted us to employ Trametinib, the MEK1/2 inhibitor FDA-approved compound for melanoma, as a tool to reduce EGR1-TFEB expression in TFEB-driven cancers." (PMID 36888606, 2023). "Recently, an important property distinguishing SB202190 from BIRB796 was identified: a SB202190-specific, p38-independent ability to robustly translocate lysosomal membrane-bound TFEB, a MITF-related protein, to the nucleus of melanoma cells." (PMID 33802847, 2021). "And BRAF-V600 inhibitor can suppress the activation of TGF-β signaling via dephosporylation of TFEB, while TFEB phosphorylation and TGF-β upregulation play a pro-tumorigenic role in BRAF inhibitor resistant melanoma." (PMID 34247571, 2021). "We have presented evidence for the inactivation of TFEB and ZKSCAN3 by the co-effect of CAP and SN and blockage of the mTOR/EGFR pathway that provides a compelling model to explain the suppression of melanoma and resultant autophagy-lysosome activation." (PMID 32178401, 2020). "Our study indicates that the CAP and SN combination dysregulated autophagy-related genes, including TFEB and ZKSCAN3, which have important functions in connecting BRAF signaling to autophagy-lysosome-mediated catabolism in melanoma." (PMID 32178401, 2020). "We show that overexpression of TFEB or MITF itself reduced the expression of endogenous MITF at both the mRNA and protein levels in two different melanoma cell lines." (PMID 32881934, 2020). "In this study, we show that the MITF, TFEB and TFE3 transcription factors are all produced in melanoma cells, albeit at different levels." (PMID 32881934, 2020). "Particularly, in the 501Mel and Skmel28 human melanoma cell lines used in this study, MITF is highly expressed whereas TFEB and TFE3 are expressed at considerably lower levels." (PMID 32881934, 2020). "Like MITF, the TFEB and TFE3 genes are expressed in melanoma cells as well as in melanoma tumors, albeit at lower levels." (PMID 32881934, 2020). "Since MITF/TFE family factors can regulate lysosomal signaling, including Wnt/β-catenin we studied TFEB and βcatenin levels in V600BRAF melanoma cell lines." (PMID 30634982, 2019). "This role of TFEB and TFE3 in immune response in melanoma needs to be explored further, as this raises important therapeutic questions about their role in immunotherapy, a key treatment option for melanoma." (PMID 30705290, 2019). "Although TFEB a broader number of gene expression beyond those in the autophagy–lysosomal pathway, abrogating autophagy–lysosomal function renders BRAFV600E-melanoma less responsive to TFEB activation." (PMID 30979895, 2019).
melanoma (continued). "Here, we show that in BRAFV600E-melanoma, autophagy is induced by BRAF inhibitor (BRAFi), as part of a transcriptional program coordinating lysosome biogenesis/function, mediated by the TFEB transcription factor." (PMID 30979895, 2019). "Our results suggest that MITF and the related factors TFEB and TFE3 have separate roles in regulating a starvation-induced autophagy response in melanoma." (PMID 30705290, 2019). "The related transcription factors TFEB and TFE3 regulate lysosomal activity and autophagy processes known to be important in melanoma." (PMID 30705290, 2019). "MITF-A is localized at the lysosomal membrane, mimicking the transcriptional regulation of TFEB and TFE3, and MITF-M drives the transcription of lysosomal markers and activates the CLEAR motif reporter in melanoma cells." (PMID 29903018, 2018). "In line with TFEB, MITF also regulates the expression of PGC1α in retinal pigment epithelium and melanomas, further confirming the role of those transcription factors in energy metabolism." (PMID 29903018, 2018). "Consistent with previous observations in melanoma, in TCGA melanoma cohort, TFE3 mRNA was inversely correlated with MITF, while a moderate anti-correlation was also noted between MITF and TFEB." (PMID 41275493, 2025). "In addition to MITF, transcription factor EB (TFEB), another member of the MiT transcription factor family, has been suggested to play a role in melanoma onset and progression." (PMID 37160873, 2023). "Here, we suggest that the oncogenic transcription factor EB (TFEB), a key regulator of lysosomal biogenesis and function, controls melanoma tumour growth through a transcriptional programme targeting ERK1/2 activity and glucose, glutamine and cholesterol metabolism." (PMID 37160873, 2023). "Our data further indicate that TFEB activities regulating melanoma cell proliferation are not limited to effects on the cell cycle but extend to the control of metabolic pathways." (PMID 37160873, 2023). "Furthermore, in BRAF-mutant melanoma cells, the increased activity of the MAPK pathway results in the inhibition of the genetic programme regulated by TFEB, leading to tumour progression and chemoresistance to BRAF inhibitors." (PMID 37160873, 2023). "Although genetic alterations of TFEB are involved in the development of tumors in kidney, exocrine pancreas, and melanomas, alterations and functions of TFEB in liver cancer have not yet been fully identified." (PMID 35625599, 2022). "The same effect was observed for TFEB and TFE3 (another MITF family member) in non-melanoma cells." (PMID 33802847, 2021). "Thus, through TFEB inhibition, oncogenic BRAF signaling is coupled to TGF-β signaling, promoting melanoma progression and de-differentiation." (PMID 30979895, 2019). "To investigate whether blocking BRAFi-induced autophagy–lysosomal activation alters melanoma response to BRAF-targeted therapy, we used TFEBKD A375 cells reconstituted with WT or mutant TFEB." (PMID 30979895, 2019). "We demonstrate that enhanced TFEB suppression via constitutive expression of a phosphomimetic mutant accelerates BRAFV600E melanoma growth, whereas its non-phosphorylatable derivative behaves in an opposite manner." (PMID 30979895, 2019). "Interestingly, TFEB and TFE3 show strong correlation with genes involved in the immune response in these tumors, implying a distinct role for these factors in melanoma tumors." (PMID 30705290, 2019). "Altogether, we have identified an unexpected activity of TFEB-mediated autophagy–lysosomal function in regulating TGF-β signaling, which when compromised, promotes tumor progression and drug resistance in BRAF-mutant melanoma." (PMID 30979895, 2019). "Thus, BRAFV600E-dependent TFEB phosphorylation and TGF-β activation enhances tumor aggressiveness, as observed in BRAF-mutant melanoma patients." (PMID 30979895, 2019). "This highlights that TFEB inactivation confers resistance rather than sensitivity to BRAF inhibition in melanoma." (PMID 30979895, 2019).
melanoma (continued). "The role and importance of localisation and heterodimerization of MITF, TFEB and TFE3 in melanoma cells remains to be explored and may reveal why MITF regulates a distinct set of genes compared to the other factors." (PMID 30705290, 2019). "Interestingly, while autophagy may either promote or suppress tumor growth, in melanoma cells, YY1 was shown to coordinate with Transcription factor EB (TFEB) and regulate genes involved in autophagy and lysosomal biogenesis." (PMID 31824839, 2019). "However, the expression of MITF negatively correlates with TFEB and TFE3 expression, raising the question whether MITF regulates a different set of lysosomal genes than the other factors in melanoma." (PMID 30705290, 2019). "The finding that the MiT-TFE factors are co-expressed in melanoma cells and tumors, together with recent evidence pointing to a role of MITF in the regulation of lysosomal and autophagy-related genes, similar to TFEB and TFE3, may suggest an overlap in function or cooperation between these factors." (PMID 32881934, 2020). "MITF, TFEB and TFE3 are expressed to some extent across melanoma tumors and cell lines, whereas TFEC is not." (PMID 32881934, 2020). "Here, we investigate the role of TFEB and TFE3 in cells that also express MITF to better understand the potential of these related transcription factors to exhibit distinct and non-redundant roles in gene expression and melanoma progression." (PMID 41275493, 2025).
Obesity (31 papers, 2016 to 2025). Accumulation of substantial excess body fat. "It ultimately upholds transcription factor EB (TFEB) and causes the nuclear transfer to foster hepatic cell lipophagy (a particular type of autophagy), healing obesity-related NAFLD." (PMID 39421288, 2024). "TFEB overexpression in the liver prevents weight gain and associated metabolic syndrome in both diet-induced and genetic mouse models of obesity." (PMID 33292395, 2020). "We have previously reported that liver‐specific loss of TFEB exacerbates diet‐induced obesity." (PMID 28283651, 2017). "In a model of diet-induced obesity, transcription factor EB (TFEB) directly bound the Siglec-15 promoter in non-small-cell lung cancer (NSCLC) cells, driving its upregulation alongside glycolytic genes." (PMID 41301440, 2025). "Overexpression of TFEB in macrophages has been reported to protect against obesity and insulin resistance via upregulation of GDF1525." (PMID 41665896, 2025). "This was seen with reduced levels of TFEB, a master regulator of lysosomal gene expression, with ethanol and obesity." (PMID 40677154, 2025). "Obesity and hyperlipidemia in the setting of adverse social determinants negatively impact NK cells via a pathway involving DUSP1/mTOR/TFEB, contributing to increased heart disease risk." (PMID 39718832, 2024). "Adipocyte-specific TFEB overexpression protect mice from diet-induced obesity, insulin resistance, and metabolic sequelae." (PMID 38424050, 2024). "To explore the potential importance of the mTOR/TFEB/LAMP1 axis in NK cells isolated from individuals W/O or WO/O obesity, we performed RT-qPCR analysis and Western blotting analysis." (PMID 39718832, 2024). "By improving lipid breakdown and decreasing adipose inflammation, TFEB-induced GDF15 protects against diet-induced obesity and insulin resistance." (PMID 39000187, 2024). "The activation of TFEB-growth differentiation factor-15 (GDF15) in macrophages can regulate metabolic disorders such as obesity induced by HFD." (PMID 39758315, 2024). "We also investigated the role of TFEB in obesity-related tubular lesions using a model of high-fat diet–fed (HFD–fed), PTEC-specific Tfeb-deficient mice." (PMID 36649084, 2023). "In an independent study, a novel TFEB activator improved the glucose tolerance and metabolic profile in genetically induced diabetes (ob/ob) and in diet-induced obesity mouse models." (PMID 34338148, 2022). "Conversely, the liver-specific overexpression of Atg7 or Transcription Factor EB (TFEB) enhances autophagy, prevents weight gain, and alleviates signs of metabolic syndrome in both diet-induced and genetic mouse models of obesity." (PMID 33445755, 2021). "TFEB overexpression was shown to protect animals from diet-induced obesity by upregulating genes that improve metabolic rate, reduce adiposity, and induce white fat browning and cold tolerance." (PMID 33490073, 2020). "Adipocyte-specific TFEB overexpression in mice is protective against diet-induced obesity, insulin resistance, and metabolic sequelae." (PMID 33292395, 2020). "Remarkably, the increase in TFEB activity in the liver can prevent and even reverse obesity, a component of the metabolic syndrome in humans." (PMID 33490073, 2020). "Third, insufficient TFEB activity and impaired autophagic flux may be involved in obesity-related vacuolar lesions in patients with CKD." (PMID 36649084, 2023). "In addition, mTOR is also involved in the transcription factors SREBPs, PPARγ/PPARα and TFEB in lipid metabolism, which is related to the development of tumours, obesity, and fatty liver." (PMID 36611986, 2023). "We then investigated the role of TFEB in the pathogenesis of obesity-related kidney disease." (PMID 36649084, 2023). "Furthermore, TFEB and LAMP-2A are decreased in cardiomyocytes of several mouse models of diabetes and obesity, demonstrating more broadly that chronic glucolipotoxicity reduces lysosomal biogenesis through TFEB dysregulation." (PMID 33457426, 2020).
Obesity (continued). "Previous study revealed that the TFEB overexpression may affect lipid catabolismm, inhibit etabolic activities, and subsequently ameliorate the obesity-related metabolic syndrome." (PMID 31303889, 2019). "In this context, it appears logical that prominent measures to induce autophagy (like spermidine administration or gene therapy with pro-autophagic transcription factors, such as TFEB) may inhibit or prevent obesity in vivo." (PMID 28771229, 2017). "Strikingly, TFEB overexpression is also able to rescue obesity in Tfe3 KO mice." (PMID 28283651, 2017). "Simvastatin maintains lysosomal biogenesis and autophagic turnover by regulating TFEB in mouse microvascular endothelial cells, thereby preventing cardiovascular complications such as endothelial barrier dysfunction with endothelial hyperpermeability in models of obesity." (PMID 38139347, 2023). "Therefore obesity-attributed hyperinsulinemia in Bif-1 KO mice may mediate the downregulation of Atg9 and Lamp1 through the activation of mTOR and suppression of TFEB signaling, and this hypothesis warrants further investigation in the future." (PMID 26857140, 2016). "In mice fed a HFHS diet that models obesity-driven MASLD, TFEB induction in KCs consistently led to a ~68% reduction in inflammatory MdM infiltration and decreased expression of inflammatory cytokine Il1b during early disease." (PMID 41665896, 2025). "The transcription factor EB (TFEB)–GDF15 axis is essential in adapting to obesity-induced metabolic stress; GDF15 acts as a ‘lysokine’ released in reaction to lysosomal stress via TFEB activation." (PMID 39000187, 2024). "The evidence suggests that TFEB may play an important role in metabolic diseases such as obesity and T2DM, as it promotes autophagic flux, and highlights the implications of TFEB signaling in various metabolic disorders." (PMID 41439967, 2025). "Together, these results strongly suggest that, for individuals exposed to aSDoH, obesity and hyperlipidemia promote NK cell dysfunction at least partially through pathways initiated by LDL involving Dusp1-mediated regulation of mTOR- and TFEB-facilitated lysosomal biogenesis." (PMID 39718832, 2024). "Intriguingly, TFEB expression was increased in macrophages of white adipose tissue (WAT) from obese mice and humans, whereas macrophage TFEB overexpression protects against obesity and insulin resistance." (PMID 36231114, 2022).